APOE (apolipoprotein E)
Diseases named in the same sentence as APOE in open-access papers (continued):
Sharing a sentence is not in itself a finding about the gene and the disease.
Cerebral atrophy (11 papers, 2007 to 2025). Atrophy (wasting, decrease in size of cells or tissue) affecting the cerebrum. "In agreement with our findings, multiple recent studies have illustrated APOE ε4 mediated accelerated cerebral atrophy in elder CN." (PMID 37323144, 2023). "This study revealed that OCT measurements were significantly correlated with MMSE and MoCA scores indicative of cognitive function, MTA and PCA scores indicative of cerebral atrophy, tau and Aβ levels in the CSF, and APOE genotypes in patients with AD." (PMID 36089740, 2022). "Besides, most early studies only focused on candidate brain regions, and studies illustrating the effect of APOE on cerebral atrophy from the whole brain’s voxel-wise perspective are still limited and remain to be further discussed." (PMID 37323144, 2023). "In addition, these changes were correlated with MRI findings indicative of cerebral atrophy, tau and amyloid‐beta levels in the cerebrospinal fluid, and APOE genotype." (PMID 36089740, 2022). "In conclusion, this large‐scale study confirmed that retinal structure was significantly altered in patients with AD and that OCT measurements correlated with cognitive function, MRI findings indicative of cerebral atrophy, tau and Aβ levels in the CSF, and APOE genotypes." (PMID 36089740, 2022). "Besides, APOE ε4 also contributed to faster cerebral atrophy during the conversion from MCI to AD." (PMID 37323144, 2023). "Gross measures of cerebral atrophy or subtle vascular pathology on MRI could not distinguish between ε4 carriers and non-carriers, and the level of subjective complaint of memory problems was not significantly related to APOE status." (PMID 17974013, 2007).
endometrial cancer (11 papers, 2015 to 2026). Primary or metastatic malignant neoplasm involving the endometrium (mucous membrane that lines the endometrial cavity). "In our review, two studies described the upregulation of APOE in endometrial cancer patients and its precursors, while one study found it to be downregulated." (PMID 39194522, 2024). "Survival analysis indicated that only APOE and BGN were related to the overall survival (OS) and disease-free survival (DFS) of endometrial cancer patients, suggesting that they can be used as biomarkers for predicting patient survival." (PMID 39650066, 2024). "We confirmed by qRT-PCR that the mRNA expression levels of APOE, BGN, BST1, and C1QB in endometrial cancer cell lines (HEC-1B and Ishikawa) were consistent with our previous results." (PMID 39650066, 2024). "The results showed that four hub genes, APOE, BGN, BST2, and C1QB, were abnormally differentially expressed in normal tissues and endometrial cancer." (PMID 39650066, 2024). "A 5-biomarker panel of cervico-vaginal fluid proteins combining APOE, GGCT, CFAB, LY6D and CEAM5 predicted advanced stage endometrial cancer with AUC 0.96 (0.92–1.00)." (PMID 38513301, 2024). "In our qRT - PCR verification, the expressions of APOE, BGN, BST1, and C1QB in endometrial cancer cell lines were different from those in normal endometrial epithelial cells, which was consistent with our analysis." (PMID 39650066, 2024). "Quantification analysis in 36 patients with endometrial cancer compared to 36 healthy individuals confirmed the upregulation of APOA1, HBB, CA1, HBD, LPA, SAA4, PF4V1, and APOE." (PMID 36551747, 2022). "Among them, APOE, BGN, BST1, and BGN showed expression differences in endometrial cancer." (PMID 39650066, 2024). "Several blood-based protein biomarker candidates for endometrial cancer detection were suggested, including the Apolipoprotein family (APOA1/4, APOC1/2/3, and APOE), Clusterin (CLU), Inter-alpha-trypsin inhibitor heavy chain (ITIH2 and ITIH4), and Antithrombin III (ATR/SERPINC1)." (PMID 39194522, 2024). "The mRNA expression levels of APOE, BST1, and C1QB in endometrial cancer cell lines were significantly higher than those in normal endometrial epithelial cells, whereas BGN expression was higher in normal endometrial cell lines than in endometrial cancer cell lines." (PMID 39650066, 2024). "The four hub genes (APOE, BST1, BGN, C1QB) with differential expression in endometrial cancer tissues may serve as potential therapeutic targets, warranting further research to validate their effectiveness as potential prognostic markers and treatment targets for endometrial cancer." (PMID 39650066, 2024). "Classical univariate ROC curve analyses confirmed the discriminatory potential of cervico-vaginal fluid derived PLTP, A2MG, APOE, FIBB, CO5 and FIBA for the detection of non-endometrioid endometrial cancers with AUC's >0.97 respectively." (PMID 38513301, 2024).
fibrosis (11 papers, 2014 to 2026). the formation of excess fibrous connective tissue in an organ or tissue in a reparative or reactive process. "Twenty-four haplotype combinations were generated from the four selected encoding genes (-627 IL10, -400 MTP, 1183 SOD2, and APOE) among Mild and Severe fibrosis groups." (PMID 33924242, 2021). "However, apolipoprotein E, which is a negative feedback inhibitor of the inflammatory response, was under-expressed in fibrosis model group." (PMID 28662027, 2017).
Hepatitis (11 papers, 2010 to 2025). Inflammation of the liver. "We conclude that the formation of the C1q-ApoE complex represents a new common pathological hallmark of major forms of human hepatitis including NAFLD." (PMID 36304458, 2022). "ApoE is also implicated in infections with herpes simplex type-1, hepatitis C and human immunodeficiency viruses." (PMID 28660014, 2017). "A clinical study should be performed in which the onset of liver inflammation in NAFLD should be more stringently defined to determine the time course of C1q-ApoE complex formation during subacute NAFLD hepatitis and the various stages of NAFLD including HCC." (PMID 36304458, 2022). "Administration of CDg16 via tail vein discriminated M1 macrophages in the liver of ApoE KO and hepatitis to the control liver tissues of wild-type mouse, indicating that CDg16 can detect M1 macrophages regardless of tissue types." (PMID 30846702, 2019). "Here, we sought to examine whether the C1q-ApoE complex develops in several forms of murine and human hepatitis and to define its localization within the liver lobule during disease progression." (PMID 36304458, 2022). "Finally, we examined the application of CDg16 to liver, another type of tissues, from control, ApoE KO and hepatitis mouse." (PMID 30846702, 2019).
Impaired glucose tolerance (11 papers, 2013 to 2024). An abnormal resistance to glucose, i.e., a reduction in the ability to maintain glucose levels in the blood stream within normal limits following oral or intravenous administration of glucose. "MIF gene interference is linked to impaired glucose tolerance, and lower blood glucose level in diabetic apoE−/− mice." (PMID 25661015, 2015). "Specifically, ovariectomized female ApoE−/−:Ins2+/Akita mice show a significant reduction in pancreatic beta cell mass and impaired glucose tolerance, compared to sham operated female ApoE−/−:Ins2+/Akita mice, and 17-beta estradiol supplementation is able to rescue this phenotype." (PMID 38339098, 2024). "In the present study, we employed a dietary regimen of a high-fat diet (HFD), a well-established and robust animal model for studying impaired glucose tolerance and early T2DM in mice, compared to a regular diet, on an APOE-targeted replacement (TR) mouse model expressing either apoE3 or apoE4." (PMID 32075060, 2020). "GCA abundance was lower by 29.7% in the DEM (P = 0.012) group and by 16.2% in the MCI group (P = 0.025) as compared to the NC group when not controlled for sex, ApoE status (E2/E2, E2/E3, E2/E4, E3/E3, E3/E4, or E4/E4), age, or impaired glucose tolerance (IGT) status (impaired or not impaired)." (PMID 36212044, 2022).
infarcts (11 papers, 2001 to 2025). "Genetic susceptibility and APOE ε4 genotype have been reported to be significantly associated with CMB and also with enhanced susceptibility to cerebrovascular insults and, thus, large infarction size." (PMID 36504664, 2022). "In contrast, STZ+HFD+UCAO induced large arterial infarction after UCAO in 22% (11/49, including three lethal infarction) of C57BL/6 mice and 31% (9/29) of ApoE-/- mice." (PMID 39744690, 2025). "TDP-43, lacunar infarcts, hyaline arteriosclerosis, and CAA did not mediate the association between APOE-ε4 and cognitive abilities." (PMID 38115150, 2023). "Four weeks after LAD occlusion, infarction size, as determined by Gomori trichrome staining, was not different between ApoE−/− mice with and without additional miR155 knockout." (PMID 34067440, 2021).
Myocardial fibrosis (11 papers, 2009 to 2026). "Since myocardial fibrosis in ApoE−/− mice develops in an age‐dependent, non‐linear manner, a direct comparison of the effects between the dietary regimes is not conclusive." (PMID 41292235, 2026). "This study demonstrated that ApoE−/− diabetic mice exhibited cardiac inflammation, myocardial fibrosis, cardiomyocyte apoptosis, increased gene expression associated with cardiomyocyte hypertrophy, and early signs of LV diastolic dysfunction." (PMID 39563316, 2024). "We have previously shown that platelet accumulation in atherosclerotic coronary arteries and myocardial fibrosis were both reduced in SR-B1/apoE dKO mice treated with the hydroxymethylglutaryl coenzyme A reductase inhibitor, rosuvastatin." (PMID 30356742, 2018). "Occasional myocardial fibrosis has been observed in 10 month old apoE KO mice." (PMID 19956623, 2009). "Under CED feeding, a statistically significant (p < .001) increase in myocardial fibrosis was observed in PACAP−/−/ApoE−/− and PAC1−/−/ApoE−/− compared to ApoE−/− mice." (PMID 41292235, 2026). "The central objective of this present study was to analyze the effects of a lack of PACAP or PAC1 in the ApoE model on myocardial fibrosis." (PMID 41292235, 2026). "However, after 10 weeks of CED, a statistically significant increase in myocardial fibrosis was detected in PACAP−/−/ApoE−/− and PAC1−/−/ApoE−/−, compared to ApoE−/− mice." (PMID 41292235, 2026). "We previously did not observe substantial coronary arterial occlusion nor myocardial fibrosis in PDZK1/apoE dKO mice fed a Western diet for three months." (PMID 19956623, 2009).
nephrotic syndrome (11 papers, 2013 to 2024). A collection of symptoms that include severe edema, proteinuria, and hypoalbuminemia; it is indicative of renal dysfunction. "Evidence from a meta-analysis of experimental and human studies suggested an association between APOE gene expression and its gene polymorphism with nephrotic syndrome susceptibility." (PMID 26830841, 2016). "A meta-analysis of experimental and human studies suggested an association between APOE gene expression and its gene polymorphism with nephrotic syndrome susceptibility." (PMID 24456740, 2014). "Patients with nephrotic syndrome and elevated ApoE levels should be prompted into renal biopsy to avoid delay of appropriate treatment and unnecessary use of glucocorticoids." (PMID 38448817, 2024). "In the nephrotic syndrome, the elevated total cholesterol and triglyceride parallelly occur with the significant increase in apoA-I, apoA-IV, apoB, apoC, and apoE levels and the apoC-III to apoC-II ratio." (PMID 37061666, 2023). "The typical clinical manifestations of LPG include proteinuria or nephrotic syndrome and elevated serum ApoE." (PMID 33663537, 2021).
Splenomegaly (11 papers, 2013 to 2025). Abnormal increased size of the spleen. "A literature search identified seven individuals with splenomegaly caused by APOE variants (deletion of leucine at position 167)." (PMID 40149441, 2025). "The eight analyzed articles reported on a total of seven patients with splenomegaly caused by the APOE variant (s)." (PMID 40149441, 2025). "In this article, we show that the differential diagnosis for an adult presenting with a macrophage storage disorder phenotype, including elevated levels of PPCS, should be broadened with dyslipidemic splenomegaly, caused by pathogenic variants in APOE." (PMID 40149441, 2025). "Although malfunctioning APOE isoforms are currently primarily perceived as risk factors for cardiovascular disease, APOE knock-out mice have confirmed a direct correlation between the loss of APOE and the development of splenomegaly." (PMID 40149441, 2025). "Characteristics of patients with splenomegaly caused by variants in the APOE gene (NM_001302688.2)." (PMID 40149441, 2025). "In addition, we performed a meta-analysis of comparable cases reported in literature to find additional evidence of the relationship between pathogenic APOE variants and the inherited dyslipidemic splenomegaly phenotype." (PMID 40149441, 2025). "In summary, patients that are under evaluation for a lysosomal storage disorder may actually suffer from dyslipidemic splenomegaly due to disruptive, heterozygous or homozygous APOE variants." (PMID 40149441, 2025). "A total of six patients presented APOE variants in combination with splenomegaly: two patients had homozygous APOE-ε1 variants, and all seven patients who were previously reported on in literature showed the same deletion of leucine 167 (NM_000041) on APOE-ε3." (PMID 40149441, 2025). "The detected homozygous missense variant c.512G>A p.(Gly171Asp), classified as class 3 (a variant of unknown significance) in ClinVar, was prioritized due to the previously reported association with splenomegaly and foam cells in bone marrow in patients with other APOE variants in literature." (PMID 40149441, 2025). "The degree of splenomegaly was assessed using the splenic index (spleen weight/body weight 100%), revealing a significantly higher degree in the model group compared to the ApoE-/- group." (PMID 40867523, 2025). "While organ size remained largely unchanged, splenomegaly was observed in WD-fed ApoE-/- mice." (PMID 40963900, 2025). "An initial assessment of the immune phenotype of apoE KO mice revealed that these mice display splenomegaly with an accumulation of CD4+CD44hiCD62Llo T cells (effector memory, TEM) but not of CD8+CD44hiCD62Llo in the spleen, and a concomitant decrease of CD4+CD44loCD62Lhi T cells (Tnaive)." (PMID 30082772, 2018).
thrombosis (11 papers, 2001 to 2025). "Authors of a hospital-based case-control study suggested that APOE E3/E4 genotype was associated with a higher lower extremity deep venous thrombosis risk." (PMID 26830841, 2016). "Recent evidence suggests that ApoE polymorphisms may influence susceptibility to deep vein thrombosis (DVT)." (PMID 41465167, 2025). "In a Chinese case-control study studying the association between the APOE gene and lower extremity deep venous thrombosis (LEDVT), the patients had a higher frequency of the APOE E3/E4 genotype compared to healthy controls." (PMID 38540308, 2024). "We found both apoE ε3/ε4 genotype and ε4 allele frequencies to be more common (non-significant) in cases with cortical thrombosis than in controls." (PMID 11434425, 2001).
thyroid cancer (11 papers, 2021 to 2025). "High expression of APOE was reported to be associated with good prognosis of thyroid cancer patients." (PMID 36092919, 2022). "Compared to their counterparts in central compartment lymph nodes, thyroid cancer cells in cervical LNMs exhibited significantly lower APOE expression." (PMID 39810624, 2025). "By combining scRNA‐seq and spatial transcriptomics, we identified a group of thyroid cancer cells with relatively low APOE expression." (PMID 39810624, 2025). "Further research is necessarily warranted to elucidate the specific impact of different APOE isoforms on thyroid cancer progression and metastasis." (PMID 39810624, 2025). "Previous studies have shown that APOE enhances the proliferation and growth of thyroid cancer cells by promoting cellular glycolysis." (PMID 40437660, 2025). "As such, similar findings were discovered with regard to LXRβ upregulation in thyroid cancer, which consequently leads to an increase in APOE expression." (PMID 38067270, 2023). "For example, one study reported that genetic variants of ferroptosis‐related APOE, BCL3, and ALOX5AP were associated with the risk of thyroid cancer." (PMID 38151984, 2023). "APOE gene expression was analyzed and revealed that it was significantly overexpressed in thyroid carcinomas, notably PTC." (PMID 38067270, 2023). "APOE mRNA expression was significantly upregulated in thyroid cancer than in adjacent normal tissues according to the GEPIA database." (PMID 35371313, 2022). "Next, we used the UALCAN web resource to explore the relationship between APOE expression and different clinical characteristics of thyroid cancer." (PMID 35371313, 2022). "Moreover, APOE expression levels were correlated with tumour‐infiltrating immune cells and immune biomarkers in thyroid cancer." (PMID 39810624, 2025). "APOE is another well-documented apolipoprotein in thyroid cancer." (PMID 38067270, 2023). "It has been found that APOE expression is upregulated in thyroid cancer." (PMID 38067270, 2023). "To further investigate whether the abnormal expression of APOE affects the occurrence of thyroid cancer, we then evaluated APOE transcription levels from multi-database." (PMID 35371313, 2022). "In addition, the APOE high-expression group were highly enriched in thyroid cancer." (PMID 35090515, 2022). "This suggests that high APOE expression may be an important characteristic of thyroid cancer." (PMID 33521130, 2021). "Here, we performed LASSO analysis and identified 6 critical fibroblasts related factors (PCOLCE2, APOD, APOE, TIMP1, HTRA3 and MT1A) and calculated the fibrosis scores based on their expression in patients with thyroid cancer." (PMID 36387901, 2022). "We found that, in thyroid cancer, the expressions of FN1, APOE, and CLU were statistically significant." (PMID 33521130, 2021). "Our RNA‐seq data from APOE‐overexpressing thyroid cancer cell lines showed increased expression of ABCA1, a cofactor in LXR activation, suggesting that APOE overexpression may induce LXR, thereby potentially rescuing impaired immunity in tumours." (PMID 39810624, 2025). "Interestingly, we found that APOE correlated with CLU via LRP2 in MCODE2, and CLU and LRP2 had common predicted miRNAs, which implicated hub genes and their potential miRNAs that might affect thyroid cancer proliferation and invasion through the extracellular matrix." (PMID 33521130, 2021). "Univariate Cox regression analysis was further applied to assess the prognostic value of DEFRGs, and we found that 4 DEFRGs (APOE, P = 0.004; TSC22D1, P = 0.025; TIMP1, P = 0.029; HTRA3, P = 0.007) may act as independent factors for overall survival of thyroid cancer." (PMID 36387901, 2022).